APOC1 (apolipoprotein C1)
Diseases named in the same sentence as APOC1 in open-access papers (continued):
Sharing a sentence is not in itself a finding about the gene and the disease.
metastatic colorectal cancer (1 paper, 2021). "APOC1 expression was significantly upregulated in CRC tumor tissues, and was higher in primary tumor lesions with metastatic colorectal cancer than that in the primary tumor lesions without metastatic colorectal cancer." (PMID 34081622, 2021).
multiple sclerosis (1 paper, 2022). A progressive autoimmune disorder affecting the central nervous system resulting in demyelination. "Cluster 3 was marked by Npl, found in lipid-droplet microglia, and Apoc1, a lipoprotein high in multiple sclerosis-associated human microglia." (PMID 35481836, 2022).
myopia (1 paper, 2025). "Macrophages in the myopia group upregulated proinflammatory Ifitm3/6, Apoc1, and Bst2-Siglech in the large intestine, proinflammatory ly6c1, Apoc1, and S100a in the liver, and ly6c1 and S100a in the kidney." (PMID 41330940, 2025).
Nephropathy (1 paper, 2024). A nonspecific term referring to disease or damage of the kidneys. "Patients with DM have a higher Apoc1 plasma level, and meta-analysis demonstrates an association between a polymorphism in Apoc1 and an increased risk of developing nephropathy." (PMID 38625739, 2024).
neuropathic pain (1 paper, 2022). Chronic pain caused by damage to nerve fibers. "Synaptic proteins such as gelsolin, apolipoprotein C1, apolipoprotein E, contactin-1, and neural cell adhesion molecule L1-like protein were altered in cerebrospinal fluid of neuropathic pain patients and contributed to pain treatment." (PMID 36545122, 2022).
non-small cell lung carcinoma (1 paper, 2024). A group of at least three distinct histological types of lung cancer, including non-small cell squamous cell carcinoma, adenocarcinoma, and large cell carcinoma. "Another study reported that APOC1 could reduce iron death in non-small cell lung cancer (NSCLC) patients through the NRF2/HO-1 pathway, which in turn inhibited the conversion of M2 to M1 macrophages for anti-PD-1 immunotherapy for NSCLC." (PMID 39511608, 2024).
Pleural effusion (1 paper, 2025). The presence of an excessive amount of fluid in the pleural cavity. "Unlike the mitochondria-associated genes in pleural effusion, BL liver metastases had elevated apolipoprotein genes, such as APOC1, APOA1, and APOE." (PMID 39955556, 2025).
preeclampsia (1 paper, 2024). Preeclampsia is a hypertensive disorder of pregnancy that is characterized by new-onset hypertension with proteinuria presenting after 20 weeks of gestation, and depending on mild or severe forms may initially present with severe headache, visual disturbances, and hyperreflexia. "The existing literature on the relationship between these proteins and preeclampsia is limited, underscoring the importance of further research to elucidate the role of APOC1 and APOL1 in the pathophysiology of preeclampsia and their potential use as biomarkers or therapeutic targets." (PMID 39201423, 2024).
prion disease (1 paper, 2014). A transmissible disease that is caused by a protein that is able to induce abnormal folding of normal cellular proteins, leading to characteristic spongiform brain changes, which are associated with neuronal loss without an inflammatory response. "Since APOC1 is able to activate cholesterol esterification via lecithin-cholesterol acyltransferase, its up-regulation could lead to an increase in cholesterol biosynthesis, consistent with the concomitant presence of prion disease." (PMID 24898206, 2014).
sarcoma (1 paper, 2023). A usually aggressive malignant neoplasm of the soft tissue or bone. "Its expression was detected together with APOE, APOC1 (apolipoprotein C1), FABP5 (fatty acid binding protein) and LIPA (Lipase A), genes involved in lipid transport and metabolism and highly detected in breast, sarcoma, colon, lung and other cancers." (PMID 37342322, 2023).
Senile plaques (1 paper, 2023). Senile plaques are extracellular deposits of amyloid in the gray matter of the brain. "In senile plaques of individuals with AD, coexistence of ApoC1 and Aβ has been observed." (PMID 37685872, 2023).
staphylococcus aureus infection (1 paper, 2023). An infectious process in which the bacteria Staphylococcus aureus is present. "The KEGG pathway enrichment analysis showed that co-expressed genes of APOC1 were mainly enriched in Staphylococcus aureus infection, antigen processing and presentation, and graft-versus-host disease pathways." (PMID 36969562, 2023).
T-cell lymphomas (1 paper, 2022). "In neoplastic B phenotypes, drastically differential increased protein levels were observed in Ig heavy chain V region GOM, clusterin, β2M, and plasminogen, while APOC1 was only notably elevated in T-cell lymphoma." (PMID 35765478, 2022). "When compared between B- and T-cell lymphomas, B-cell phenotypes had upregulated immunoglobulin (Ig) heavy chain V region GOM (p=0.02), clusterin (p=0.01), apolipoprotein C1 (APOC1, p=0.05), and plasminogen (p=0.02)." (PMID 35765478, 2022).
transmissible spongiform encephalopathies (1 paper, 2011). "Several studies have also reported the involvement of many members of the apolipoprotein gene family (ApoA1, ApoA4, ApoC1, ApoC2, ApoC3 and ApoD) in transmissible spongiform encephalopathies." (PMID 21629698, 2011).
tumor (77 papers, 2008 to 2026). "While several current articles have established the association between APOC1 and tumor immunomodulation, as well as the phenotypic transition of macrophages, there is a lack of exploration regarding the function of APOC1 in OV." (PMID 38515073, 2024). "In this study, combining biological information analysis with in vitro cell assays, we aim to investigate the potential association between APOC1 and tumor immunity, as well as cancer promotion." (PMID 38515073, 2024). "Tumor immune infiltration analysis showed that APOC1 and CEP55 expression is associated with immune regulatory pathways and the function of multiple infiltrating immune cells." (PMID 38172247, 2024). "AKAP1 expression is associated with APOC1 overexpression, promotes tumor progression, and has a poorer prognosis for patient survival." (PMID 36591507, 2022). "Although numerous studies revealed that ApoC-1 is associated with the tumour progression but the exact underlying mechanism and signaling pathway of ApoC-1 in tumours is still unclear." (PMID 36381193, 2022). "Very recently, APOC1 has been identified as a tumor-associated gene involved in the process of human cancers." (PMID 33430855, 2021). "We found that high expression of APOC1 was significantly associated with the larger tumor size (p = 0.018) and advanced histological grade (p = 0.016)." (PMID 32974161, 2020). "Notably, the levels of APOC1 in OV exhibit a correlation with the presence of M2 Tumor-associated Macrophages (TAMs)." (PMID 38515073, 2024). "Although APOC1 has been observed to be crucial for the growth and metastasis of a number of malignancies, the underlying mechanisms have not been fully understood, particularly with regard to its function and part in tumor immunity." (PMID 36908705, 2023). "In addition, APOC1 was significantly associated with tumor immune infiltrating cells and immune chemokines." (PMID 36969562, 2023). "Finally, an in vitro knockdown method was used to assess how APOC1 expression in tumor-associated macrophages (TAMs) affected CRC cancer cell growth and migration." (PMID 36908705, 2023). "Furthermore, the cancer stages and tumor grade of ccRCC appeared to be strongly linked with APOC1 expression according to UALCAN database." (PMID 32974161, 2020). "Moreover, by analyzing the associations between APOC1 expression and the clinicopathological characteristics of patients with ccRCC, we confirmed the correlation between APOC1 expression and tumor size, which reflects the tumor's aggressiveness." (PMID 32974161, 2020). "Besides, ApoC1 expression is remarkably associated with tumor classification and clinical stage." (PMID 36506554, 2022). "For instance, downregulation of Apolipoprotein C1 (APOC1) has been shown to increase iron and ROS levels in TAMs, triggering ferroptosis and promoting M2-to-M1 repolarization, which impairs tumor growth." (PMID 40427384, 2025). "Inhibition of APOC1 demonstrated a significant reduction in tumor progression and an altered immune cell profile favorable for enhancing the efficacy of anti-PD-1 immunotherapy." (PMID 39150660, 2025). "From an initial set of 76 patients diagnosed with PTC, we utilized qRT-PCR to assess the expression levels of four characteristic genes associated with OSPTCC subtypes (APOE, APOC1, DEPTOR, and SQSTM1) in patient tumor samples." (PMID 40650680, 2025). "The macrophage lineage was further divided into predominant populations: suppressive (SPP1+, APOC1+), pro-tumour (VEGFA+, MKI67+), inflammatory (C1QC+), classical (CD14+) and non-classical cells (CD16+)." (PMID 39788719, 2025). "Building on these findings, our results underscore the potential of targeting APOC1 to inhibit tumor angiogenesis by suppressing the PI3K/AKT/mTOR pathway." (PMID 39873475, 2025).
tumor (continued). "MMP-2 and MMP-9, known to promote tumor invasion and metastasis by degrading the extracellular matrix and basement membrane, were significantly downregulated in APOC1-knockdown cells, as shown by Western blot analysis (P < 0.0001)." (PMID 39873475, 2025). "Within the tumor microenvironment, APOC1 expression is positively correlated with CD8+T cells and NK cells that are anti-tumor immune cells." (PMID 38853203, 2024). "In terms of residual tumour presence, APOC1 expression levels were significantly higher in the R1 and R2 groups than in the R0 group (p < 0.001)." (PMID 39098992, 2024). "The interaction between ACKR2 and CCL13, CCL7 illustrates that SLC40A1+ TAMs and APOC1+ TAMs be recruited by ECs to modulate tumor immunity." (PMID 39232806, 2024). "This provides new insights into the mechanisms by which APOC1 regulates macrophage polarization within the tumor microenvironment and reveals its potential role in tumor-associated immune modulation." (PMID 39877420, 2024). "Through the inhibition of immune checkpoint blockers, APOC1 further modifies the immune microenvironment, improving the effectiveness of anti-tumor immunotherapy." (PMID 38853203, 2024). "Through localization analysis, it was determined that M2 macrophages exhibited the highest expression levels of PDE4C and APOC1, while tumour cells displayed comparatively lower levels." (PMID 38774995, 2024). "Towards the end of the pseudotime, SLC40A1+ TAMs and APOC1+ TAMs functioning pro-tumor effects began to prevail." (PMID 39232806, 2024). "In the wound healing assay using the MDA-MB-231 and MDA-MB-468 cell lines, co-cultured macrophages significantly promoted the migration of tumor cells, while APOC1-silenced TAMs largely reversed this effect." (PMID 39877420, 2024). "The significant upregulation of SIRPA-CD47 confirms the regulatory effect of ECs on TAMs and also reveals the immunosuppressive action of APOC1+ TAMs against anti-tumor immunity." (PMID 39232806, 2024). "Recent research has also found that APOC1 facilitates the M2 macrophages polarization through ferroptosis, thereby remodeling the tumor immune microenvironment." (PMID 39877420, 2024). "In summary, these findings indicate that APOC1 is predominantly expressed in macrophages, and its role in tumor immunity is likely mediated through its impact on macrophage function." (PMID 39877420, 2024). "APOC1 +APOE+ TAMs promote distant metastasis of ESCC by aiding tumor colonization in the lymph nodes through matrix reorganization, collagen deposition, and MEM." (PMID 37664173, 2023). "To understand the expression status of APOC1 in tumor tissues, adjacent tumor tissues, and normal tissues, we analyzed the expression of APOC1 in various types of tumors from the TCGA(10534 patients) and GTEx (15776 patients) databases." (PMID 36969562, 2023). "Based on the TCGA portal, we discovered in the current study that the expression of APOC1 in tumor tissues, including CRC, was obviously higher than that in normal tissues." (PMID 36908705, 2023). "Systematic pan-cancer analysis identifies APOC1 as an immunological biomarker that regulates macrophage polarization and promotes tumor metastasis." (PMID 37305534, 2023). "Given that current targeted drug therapy against tumors benefits patients with a wide range of tumors, in this study we also analyzed the relationship between APOC1 and various tumor control-related genes." (PMID 36969562, 2023). "The selection of APOC1 to study its role in the CRC tumor microenvironment was inspired by our research group." (PMID 36908705, 2023). "Compared with primary tumor, higher abundance of APOC1+APOE+ macrophages were observed in tumor nest of metastatic lymph node." (PMID 36709495, 2023). "The significance of APOC1 in the tumor immune microenvironment is substantially expanded by our findings." (PMID 36908705, 2023).
tumor (continued). "In the present study, we analyzed the correlation of APOC1 expression with immune checkpoint markers and tumor immune infiltrating lymphocytes." (PMID 36969562, 2023). "Previous studies have shown that inhibition of APOC1 transcription can promote the transformation of M2 macrophages to the M1 type via the tumor-suppressing activity of the ferroptosis pathway." (PMID 37854606, 2023). "The purpose of this work was to investigate the APOC1 gene's expression patterns in the CRC tumor microenvironment and, using the findings from bioinformatics, to assess the biological function of APOC1 in the development of CRC." (PMID 36908705, 2023). "To further explore the relationship between APOC1 expression and tumor-infiltrating lymphocytes (TILs), we examined the relationship between TILs and APOC1 expression through the TISIDB website." (PMID 36969562, 2023). "The TCGA portal revealed that the expression of APOC1 was higher in tumor tissues, including CRC, than in normal tissues." (PMID 36908705, 2023). "Apolipoprotein C-1 (APOC1) as a member of the apolipoprotein family that acts as a tumor promoter in various cancers." (PMID 37981873, 2023). "Of note, a high mRNA expression can occur without a subsequently elevated protein synthesis, the cellular subpopulations of the tumor that shed ApoC1 into the blood stream being subject to further translational control." (PMID 36216850, 2022). "Among the six TAM clusters, MHC-II TAM (cluster 14) highly expressed HLA-DRB5, APOE, and APOC1, and was more enriched in tumor core than in tumor-normal interface." (PMID 36423636, 2022). "Among them, Module2 (highly express RNASE1, C1QA, CD163, CD14, C1QC, FCGRT, and MS4A7) and Module10 (highly express APOC1, CTSB, CTSL, and TYROBP) are more likely to display the characteristics of tumor-associated macrophages (TAMs)." (PMID 35990663, 2022). "Serum levels of apolipoprotein ApoC1 have been described in a number of systemic tumor entities as potential biomarkers, but little is known about ApoC1 in neurosurgical patients." (PMID 36101402, 2022). "Recent reports have described the role of ApoC1 in malignant tumors of internal organs, exerting an impact on tumor growth and prognosis." (PMID 36101402, 2022). "Our study established a novel six‐gene (APOC1, GLTP, ISG20, SPP1, SLC24A3 and UPP1) signature that was closely associated with the immune response and tumour immune microenvironment." (PMID 34498424, 2021). "The q-PCR results validated these two ASEs, which were confirmed to play a key role in tumour metastasis and were located in the APOC1 (P = 0.0001) and SPHK1 genes (P = 0.0391)." (PMID 34857818, 2021). "Our study established a novel six‐gene (APOC1, GLTP, ISG20, SPP1, SLC24A3 and UPP1) signature that was closely associated with the immune response and the tumour immune microenvironment." (PMID 34498424, 2021). "Compared with controls, mice with in vivo knockdown of APOC1 presented a smaller tumor volume and lower tumor weight, suggesting that the growth of RCC was slowed down." (PMID 33430855, 2021). "Increasing evidence demonstrated that APOC1 gene promotes tumor progression and tumor cell migration." (PMID 34081622, 2021). "ZEB1-AS1 expression in CRC tumor tissues was similar to APOC1 expression, and miR-335-5p expression was up-regulated in CRC tumor tissues but its expression was down-regulated in CRC with metastasis." (PMID 34081622, 2021). "APOE, APOC1, and SPP1 were highly expressed in tumor-associated macrophages resulting in anti-inflammatory macrophage phenotypes." (PMID 34697289, 2021). "Our observation found higher APOC1 expression in advanced tumor malignancy characterized by tumor grade and cancer stage of ccRCC." (PMID 32974161, 2020). "Given that APOC1 was upregulated in ccRCC tissues and its high expression led to shorter OS, we further investigated the role of APOC1 in the tumor progression of ccRCC based on the cancer stage and tumor grade." (PMID 32974161, 2020).